CD44 (CD44 molecule (IN blood group))
Diseases named in the same sentence as CD44 in open-access papers (continued):
Sharing a sentence is not in itself a finding about the gene and the disease.
head and neck cancer (continued). "Thus, CD44 is believed to be a stem cell marker in head and neck cancer as in other cancers." (PMID 24403253, 2013). "Overall, bioinformatic processing of large numbers of global gene expression analyses demonstrated elevated CD44 expression in head and neck cancer relative to other cancer types, and that the application of standard cell culture protocols might decrease CD44 expression." (PMID 22242150, 2012). "The assessment of overall more than 15000 gene expression analyses showed that head and neck cancers had elevated expression compared to the majority of other solid cancers, and also, that CD44 expression levels might decrease from application of culturing protocols." (PMID 22242150, 2012). "CD44, a hyaluronic acid (HA) receptor, and CD133, also known as prominin-1, have been considered potential CSC markers in head and neck cancer." (PMID 38966069, 2024). "In a study of head and neck cancer, TAMs can affect CD44 signal through PI3K-4EBP1-SOX2 pathway to mediate stemness enhancement, and In vivo experiments, Targeting CD44 reduced PI3K-4EBP1-SOX2 signal, inhibited tumor growth, and attenuated stemness." (PMID 35479325, 2022). "CD44, a hyaluronic acid (HA) receptor has been considered as a potential CSC marker in head and neck cancer." (PMID 35274800, 2022). "Head and neck cancer stem cells (HNCSCs) have been previously identified using CSC-specific markers, the most common being CD44, Aldehyde Dehydrogenase 1 (ALDH1), and CD133." (PMID 34831291, 2021). "Diverse sub-populations of head and neck cancer stem cells (HNCSCs) have been identified previously using CSC specific markers, the most common being CD44, Aldehyde Dehydrogenase 1 (ALDH1), and CD133, or by side population assays." (PMID 34831291, 2021). "Here, we analyzed global microRNA (miRNA) expression in CD44 standard form (CD44s)-expressing SAS cells, and we identified miR-629-3p as being responsible for acquiring anticancer drug resistance in head and neck cancer." (PMID 32244823, 2020). "To investigate the relationships between EMT, CSCs and TRAF6 in head and neck cancer, we discovered that the expression of TRAF6 in SCCHN was significantly correlated with EMT markers (i.e. Vimentin and Slug) and CSC markers (i.e. CD44, KLF4, ALDH1 and SOX2)." (PMID 29193723, 2018). "CD44 is constitutively expressed in permanent cell lines of HNSCC and head and neck cancer cases were found to be CD44-positive in almost 60%." (PMID 29693014, 2018). "Formation of the CD44-Nanog-STAT-3 complex by 500 kDa HA and subsequent upregulation of miR-21 and downregulation of PDCD4 has also been demonstrated in head and neck cancer cells (HSC-3)." (PMID 30513961, 2018). "CD44 was not only found to be constitutively expressed in the HNSCC cell lines, but also abundantly expressed in head and neck carcinomas." (PMID 24612587, 2014). "Head and neck cancer cells belonging to the stem cell population are distinguished by the high expression of certain surface proteins (e.g., CD10, CD44, CD133), pluripotency-related transcription factors (SOX2, OCT4, NANOG), and increased activity of aldehyde dehydrogenase (ALDH)." (PMID 37453969, 2023). "It’s reported that interaction between matrix hyaluronan (HA) and CD44 (an HA receptor) promotes c-Jun phosphorylation followed by phospho-c-Jun nuclear translocation and co-localization with HPV16 E6 in the nucleus of HPV+ head and neck cancer cells." (PMID 36163022, 2022). "Furthermore, detailed head and neck cancer CSC biomarkers and their transcription factors are reviewed as CD44, CD133, ALDH, cMET and Oct-4, Nanog, Sox2, respectively." (PMID 30875950, 2019). "Although CD44 alone is not sufficient for precisely isolating CSC in head and neck cancer cells, the CD44 expressing cells appear to have elevated tumorigenicity." (PMID 23662112, 2013).
head and neck cancer (continued). "Bioinformatics readouts, from a total of more than 15,000 analyses, implied an increased CD44 expression in head and neck cancer, including increased expression levels relative to many normal and tumor tissue types." (PMID 22242150, 2012). "Notably, for cancer type, the negative effect of CD44 on chemotherapy treatment outcomes is the highest in breast and head and neck cancer (72% and 75% of the studies)." (PMID 38542115, 2024). "Interestingly, the Danish Head Neck Cancer Study Group randomised trial showed that mild acceleration of radiotherapy was more effective in well-differentiated HNSCC cases, expected to have a higher percentage of CD44+ cells according to our study." (PMID 22333601, 2012). "Whilst total CD44 expression is not considered to confer a survival advantage to head and neck cancers, further investigation is warranted to determine whether its variant isoforms might offer a survival advantage or stem cell properties to malignant keratinocytes." (PMID 22242150, 2012).
oral cancer (82 papers, 2013 to 2025). "The re-expression of stemness markers such as Oct-4, c-Myc, Nanog and CD44 in oral cancer tissues and their association with recurrence provides a platform for Scientists to explore their significance in predicting poor prognosis." (PMID 34885003, 2021). "Salivary rinses contain measurable biomarkers including soluble CD44 (solCD44) and total protein, which are known markers of oral cancer risk." (PMID 33530399, 2021). "A point-of-care (POC) IVD was developed to detect the presence of CD44 in a saliva sample to evaluate the risk of oral cancer." (PMID 34359370, 2021). "The BeVigilantTM Rapid Test (Vigilant Biosciences, Florida, FL, USA) is a CE-approved POC IVD, which qualitatively identifies the presence of soluble CD44 (sCD44) and total protein levels in patients at risk of oral cancer." (PMID 34359370, 2021). "Recent evidence has demonstrated that CSCs in oral cancer express the surface marker CD44, which has been reported to have multiple splicing variants." (PMID 32244823, 2020). "Previous studies have reported that oral cancer cells switch from expressing the CD44 variant form (CD44v) to expressing the standard form (CD44s) during the acquisition of CDDP resistance, which results in epithelial to mesenchymal transition (EMT) induction." (PMID 32244823, 2020). "High CD44 serum concentration and CD44v6 expression are remarkably associated with local recurrence and adverse clinical outcomes in oral cancer." (PMID 33303029, 2020). "A subsequent study from Taiwan revealed that the gene-environment interactions between CD44 rs187115 polymorphism and betel quid chewing and smoking increase the risk of oral cancer." (PMID 31682231, 2019). "Prominin-1 (CD133) and CD44 are stemness-related markers found in a variety of human tumors, including oral cancer, and the expression of these markers has been associated with the survival and prognosis of OSCC patients." (PMID 31878324, 2019). "In oral cancer cells, upregulated expression of miR-145 causes reduction in cancer stemness features, including self-renewal and invasion and CD44 expression, suggesting the critical role of miR-145 in oral cancer pathogenesis." (PMID 31530793, 2019). "Chou reported that gene–environment interactions between CD44 polymorphisms and betel quid chewing and tobacco smoking increased susceptibility to developing oral cancer." (PMID 28008391, 2016). "Our results suggest that gene–environment interactions between the CD44 polymorphisms and betel quid chewing and tobacco smoking increase the susceptibility to oral cancer development." (PMID 24699672, 2014). "We determined that the CD44 rs187115 polymorphism carriers with the genotype AG, GG, or AG+GG were associated with oral cancer susceptibility." (PMID 24699672, 2014). "The effects of CD44 on human cancer metastasis and prognosis have been well documented, but the effects of CD44 gene SNPs and environmental carcinogens on oral cancer susceptibility and clinical features remain poorly investigated." (PMID 24699672, 2014). "In conclusion, our results suggested that gene–environment interactions between the CD44 polymorphism and betel quid chewing and tobacco smoking alter the susceptibility to oral cancer development." (PMID 24699672, 2014). "In this study, we provided novel information on the effects of CD44 on oral cancer susceptibility, and elucidated the interactions of environmental risk factors and clinicopathologic statuses." (PMID 24699672, 2014). "Adjusted odds ratio (AOR) and 95% confidence interval (CI) of oral cancer associated with CD44 genotypic frequencies and smokers among 552 betel nut consumers." (PMID 24699672, 2014). "Adjusted odds ratio (AOR) and 95% confidence interval (CI) of oral cancer associated with CD44 genotypic frequencies and betel nut chewing among 731 smokers." (PMID 24699672, 2014).
oral cancer (continued). "Based on a review of the relevant literature, our study is the first to demonstrate a significant association between the CD44 rs187115 A/G polymorphism and the risk of oral cancer." (PMID 24699672, 2014). "Regarding oral cancer, previous studies have suggested a statistically significant association between smoking and CD44 expression in SCCs located in the oropharynx, hypopharynx, and larynx." (PMID 24971320, 2014). "In the present study, a case–control investigation was performed for 6 SNPs located in the promoter region or the 3′UTR of CD44 to analyze their contribution and the associations between environmental factors and oral cancer clinicopathologic characteristics." (PMID 24699672, 2014). "However, numerous studies on oral carcinoma reported contradictory results, finding that CD44 overexpression was significantly associated with poorer histopathologic differentiation, higher tumour budding, invasion, lymph node status and metastasis." (PMID 34944493, 2021). "The genetic and secretome profiling of the CD44+ CSCs could serve as diagnostic and prognostic tools in the treatment of oral cancers." (PMID 34205649, 2021). "In addition, gene-environment interactions exist in oral cancer; CD44 polymorphisms and betel quid chewing or tobacco smoking enhance the susceptibility to oral cancer occurrence." (PMID 33925911, 2021). "Therefore, we used the core-fucose-deficient anti-CD44 mAb (5-mG2a-f) for treating CD44-expressing oral cancers." (PMID 33000243, 2020). "Finally, we also observed that the stage III and IV oral cancer patients had higher frequencies of CD44 rs187115 polymorphisms with the variant genotype (AG+GG) compared with the wild-type (WT) carriers." (PMID 24699672, 2014). "Our analysis suggested that CD44 is related to worse T category, N category, tumor grade and prognosis, in pharyngeal and laryngeal cancer, but no clear association was revealed between CD44 expression and oral cancer." (PMID 24410905, 2014). "Patients with CD44 rs187115 variant genotypes (AG+GG) were correlated with a higher risk of oral cancer development, and these patients may possess greater chemoresistance to advanced- to late-stage oral cancer than WT carriers do." (PMID 24699672, 2014). "Patients who carried the functional CD44 variant rs187115 G might possess greater chemoresistance to advanced- to late-stage oral cancer than WT carriers do, and CD44 rs187115 might act as a marker to predict poor prognoses in OSCC patients." (PMID 24699672, 2014). "In conclusion, CD44 can serve as a potential diagnostic and prognostic biomarker for HNSCC34 and oral cancer, offering new molecular targets for CD44-targeted therapy for cancer management." (PMID 40738059, 2025). "In the heterogenous primary cancer cell cultures generated from oral cancer patients, only a small subpopulation (below 1%) of cells were CD44+." (PMID 39941011, 2025). "We have demonstrated previously that CD44 is a valuable marker useful for oral cancer stem‐like cell isolation." (PMID 40399621, 2025). "The relationship between CD44 and clinicopathological features of oral cancer still remains inconclusive." (PMID 41303421, 2025). "In conclusion, miRNA-21 plays a critical role in the regulation of oral cancer CD44+ cells properties." (PMID 39851519, 2025). "Survivin‐2B‐specific cytotoxic T lymphocytes were produced and evaluated for their ability to target CD44+ (cancer stem‐like cells) and CD44− cells (non‐cancer stem‐like cells), respectively, from oral cancer cell lines (HSC‐2 and HSC‐3, respectively)." (PMID 40399621, 2025). "We aimed to study the effect of the iBET JQ1 combined with miR-21 silencing on oral cancer stem cells (CD44+ cells)." (PMID 39941011, 2025). "A study in the United States showed that soluble CD44 (cluster of differentiation 44), a simple and inexpensive marker of cancer stem cells, increased in oral cancer patients who ate more green salad." (PMID 39594007, 2024).
oral cancer (continued). "A recent study showed that OCSC-derived small EVs from CD133+ CD44+ oral cancer cells transport the lncRNA UCA1, which binds to miR-134, thus modulating the PI3K/AKT pathway through LAMC2." (PMID 39200273, 2024). "This was the first study to show that increased green salad intake is associated with improved progression-free and overall survival and lower CD44 levels in mouthwash from oral cancer cases with long-term follow-ups." (PMID 39594007, 2024). "An increase of miR-494 can inhibit ALDH1 activity, CD133 positivity, and other stemness signatures in ALDH1+CD44+ oral cancer cells." (PMID 37065869, 2023). "In oral cancer, CD44 governs the invasive and metastatic potential of cells, especially the cancer stem cell sub-population by modulating the PI3K/Akt/GSK3β pathway." (PMID 37316916, 2023). "The overexpression of CD44 correlated with poor overall and disease-free survival in patients with advanced oral carcinomas." (PMID 37453969, 2023). "Because CD44 is highly expressed in oral cancer cells, the addition of HA makes the hydrogel more binding to oral cancer cells and increases the immobility of the hydrogel formed in situ." (PMID 36421563, 2022). "To date, several methods have been used to identify CSCs in oral cancer, such as the positivity of CD44, CD133, and aldehyde dehydrogenase (ALDH) activity." (PMID 35682836, 2022). "In oral cancer, the detection of circulating CD44 levels has recently been proposed as a non-invasive prognostic method." (PMID 36005828, 2022). "CD44 + cells in slow-cycling human oral carcinomas express high levels of the fatty acid receptor CD36 and lipid metabolism genes to initiate metastasis." (PMID 35892853, 2022). "Of note, p75NTR expression has been suggested by others to be prognostic when in combination with the marker CD44 in esophageal, hypopharyngeal, and oral carcinomas, as well as in HNSCC." (PMID 35681602, 2022). "In their study, CD44 bright cells isolated from human oral carcinomas exerted a distinctive ability to overexpress both the fatty acid receptor CD36 and lipid metabolism genes, thus accelerating the initiation of metastasis." (PMID 33917064, 2021). "Crosstalk between Raf-MEK-ERK and PI3K-Akt-GSK3β signaling can promote chemoresistance, progression and stemness through regulating the expression of CD44 in oral cancer." (PMID 34949193, 2021). "In agreement with our study, ERK and PI3K signaling have been reported to promote migration/invasion abilities of oral cancer cells through the expression of CD44." (PMID 34439211, 2021). "CD44 is cleaved and released in soluble form (solCD44) from the surface of cells by metalloproteinases that are overexpressed in advanced oral cancers." (PMID 34359370, 2021). "In conclusion, our study shows soluble CD44, a cancer stem cell marker that can be measured simply and inexpensively, is elevated in oral cancer patients who eat less green salad." (PMID 33530399, 2021). "The oral cancer patients with positive expression of the stem cell markers such as Oct-4, CD44 and c-Myc showed resistance to radio-chemo therapies." (PMID 34885003, 2021). "Oral cancer patients who consumed at least one serving per week of green salad were found to have significantly lower CD44 levels than those who ate salad less frequently (mean of log2[solCD44]1.73 versus 2.25, p = 0.014)." (PMID 33530399, 2021). "This case-control study demonstrates that subjects who consumed less green salad had higher CD44 levels and were more likely to be diagnosed with oral cancer." (PMID 33530399, 2021). "Metformin, a well-known first-line drug for diabetes treatment, was found to be capable of down-regulating CSC marker CD44 in primary oral cancer cells." (PMID 33303029, 2020).